PRL (prolactin)
Diseases named in the same sentence as PRL in open-access papers (continued):
Sharing a sentence is not in itself a finding about the gene and the disease.
Microprolactinoma (continued). "By contrast, patients with microprolactinomas may have prolactin levels < 100 ng/mL, as seen in 16.5% of the patients in the present study." (PMID 39420933, 2024). "A larger sample size, assessment of not only total but also monomeric prolactin, and a small (25–31%) proportion of individuals with prolactin-secreting tumors (only microprolactinomas) may account for the inconsistency with previous findings." (PMID 37242186, 2023). "Serum PRL was 18,325 μIU/mL, and an MRI revealed a microprolactinoma of 2.1/2 mm." (PMID 36556282, 2022). "Our study confirms the notion that primary surgery may be a more effective method to achieve final remission in microprolactinoma patients with a preoperative PRL level of ≤200 ng/mL." (PMID 34504526, 2021). "Therefore, our findings support that a preoperative PRL level of <200 ng/mL is a strong predictor of microprolactinoma remission after surgery." (PMID 34504526, 2021). "In conclusion, modern TSS has a high final remission rate in treatment-naive microprolactinoma patients and may be an alternative first-line treatment option in addition to DA, particularly in those with preoperative PRL level of <200 ng/mL." (PMID 34504526, 2021). "However, recent studies have reported high PRL normalisation rates after surgery for microprolactinomas that were near or superior to DA treatment." (PMID 34504526, 2021). "Given that the beneficial effects of menopause on microprolactinomas are supposed to be due to a reduction of circulating estrogens, we tested whether a correlation exists between estradiol and prolactin." (PMID 31001736, 2019). "However, two patients with microprolactinoma restarted treatment on their doctors’ decision when their PRL levels increased two years after the suspension of DA." (PMID 26909481, 2016). "The inhibitory effect of RE on PRL synthesis may be useful in the treatment of prolactinoma, particularly with microprolactinoma where the predominant aim of therapy is to decrease the high level of PRL and improve endocrine symptoms." (PMID 24669252, 2014). "In patients with microprolactinomas, macroprolactinomas or idiopathic hyperprolactinemia, normal prolactin secretion was achieved in 76% of 997 patients treated with bromocriptine, 87% of 98 patients who received pergolide, and 89% of 612 cabergoline-treated patients." (PMID 20478050, 2010). "Transsphenoidal surgery is the surgical method of choice, with success rates in centers with experienced neurosurgeons (based on normalization of prolactin levels) of approximately 75% in patients with microprolactinomas and 34% in patients with macroprolactinomas." (PMID 20478050, 2010). "However, serum prolactin levels <100ng/mL can occur in 25% of microprolactinomas." (PMID 40960781, 2025). "For example, patients with a mildly raised prolactin with associated clinical symptoms can be treated regardless of whether there is a microprolactinoma (with MR imaging done prior to Cabergoline withdrawal if appropriate)." (PMID 38098129, 2023). "Conversely, men with microprolactinoma showed a significant increase in hematocrit (HCT) and hemoglobin (Hb) levels after PRL normalization (median HCT 42.3 vs.44.0%; Hb 14.5 vs. 15.1 g/dL; both p < 0.005)." (PMID 39900728, 2025). "Surgery showed a high remission rate in treatment-naive microprolactinoma patients after treatment withdrawal and may be an alternative first-line treatment strategy in addition to DAs, particularly in patients with a preoperative prolactin level of ≤200 ng/mL." (PMID 34504526, 2021). "Likewise, 5 patients with microprolactinomas had prolactin recovery < 40% in the PEG precipitation test, a finding indicative of macroprolactinemia but, in these cases, the value of monomeric prolactin was above the normal range." (PMID 39420933, 2024). "Among several studies such PRL level can be recognized as “grey zone” and belongs to possible pitfalls especially differentiating microprolactinomas with non-functional PA." (PMID 38375408, 2024).
Microprolactinoma (continued). "By contrast, among subjects with microprolactinomas, only 12.5% were asymptomatic, with the absence of symptoms prevailing in patients with prolactin < 100 ng/mL." (PMID 39420933, 2024). "Despite a suboptimal prolactin level, a case of microprolactinoma with no residual tumor after surgery showed no tumor recurrence at follow-up." (PMID 36950000, 2023). "The difference of the preoperative PRL levels between cystic prolactinomas and solid microprolactinomas was not statistically significant (p = 0.692)." (PMID 37143054, 2023). "This difference makes sense, since all of our patients were selected with a systematic measure of prolactin (unlike in general population), and because the real prevalence of microprolactinoma in young women is likely to be underestimated." (PMID 35250884, 2022). "Additionally, the patient with microprolactinoma whose treatment was stopped before menopause maintained normal PRL levels throughout menopause." (PMID 26909481, 2016). "Indeed, microprolactinomas (MIC) (diameter < 10 mm) usually result in PRL levels of 100-200 ng/mL, but not infrequently, they may be < 100 ng/mL, and occasionally reach 500 ng/mL or more." (PMID 29768629, 2018). "Given the lack of pituitary macroadenomas and rarity of visible microprolactinomas in our cohort, it remains to be determined under which criteria a dedicated MRI or CT scan of the pituitary gland should be considered if an adult with PWS is found to have a raised prolactin." (PMID 34441908, 2021).
polycystic ovary syndrome (47 papers, 2005 to 2025). A disorder that manifests as multiple cysts on the ovaries. "Another proposed mechanism is founded on the association of PCOS with hyperandrogenemia and relatively high estrogen levels, which could stimulate PRL secretion." (PMID 38004264, 2023). "However, elevated PRL levels suppress ovulation and can be the cause of polycystic ovaries." (PMID 40362476, 2025). "When there is an increase in prolactin levels, a condition called hyperprolactinemia occurs, which is linked with various diseased conditions, including primary hypothyroidism, prolactinoma, and polycystic ovary syndrome (PCOS)." (PMID 36551029, 2022). "Patients with polycystic ovarian syndrome (PCOS) have low hypothalamic dopaminergic tone leading to inappropriate prolactin and LH secretion." (PMID 36246929, 2022). "In this study, an animal model of hyperandrogenemia was developed using ovary-intact female rats, and the changes in expression levels of gonadotropin subunits and prolactin genes were determined." (PMID 36311909, 2022). "The effects of low dose estrogen and Vitex agnus-castus on the normalization of the menstrual cycle and the means of serum prolactin and free testosterone levels in the women with polycystic ovary syndrome were similar." (PMID 29744355, 2018). "This randomized clinical trial was done on 110 polycystic ovary syndrome women with increased serum prolactin concentration [1.5 fold more than normal level (>37.5 ng/ml)]." (PMID 25999998, 2015). "The prolactin levels in the present mutants were found to be high, and histopathological studies show that some of these animals do have polycystic ovaries." (PMID 22363892, 2011). "The aim of this study is to evaluate the effects of ovarian drilling on the serum prolactin levels and its relation to ovulation in women with polycystic ovary syndrome." (PMID 16083511, 2005). "Additionally, a thorough hormonal evaluation of the teenager with hyperandrogenemia is crucial, including prolactin, serum cortisol, insulin-like growth factor I (IGF-I), TSH and free T4." (PMID 26351529, 2015). "Studies have also demonstrated a correlation between peak prolactin and luteinizing hormone (LH) secretion in women with polycystic ovary syndrome (PCOS)." (PMID 40656428, 2025). "Women with epilepsy (WWE) commonly exhibit reproductive disturbances, including menstrual irregularities, polycystic ovary syndrome (PCOS), and dysregulation of estrogen, androgen, and prolactin (PRL) levels." (PMID 41323226, 2025). "Conversely, two other studies demonstrated a negative correlation between prolactin levels and triglycerides in patients diagnosed with polycystic ovary syndrome and those who were overweight or obese." (PMID 38399363, 2024). "These hormonal conditions include polycystic ovary syndrome (PCOS), endometriosis, premature ovarian failure (POF), hypothalamic dysfunction, hyperprolactinemia (too much prolactin), uterine fibroids, and pelvic inflammatory disease (PID)." (PMID 34646552, 2021). "Women with polycystic ovary syndrome (PCOS) are reported to have different levels of prolactin (PRL) compared to women without PCOS." (PMID 36552931, 2022).
psychosis (46 papers, 2006 to 2025). "Childhood trauma or a lack of a good relationship with one parent is associated with worse metabolic and prolactin profiles in first-episode psychosis patients during the first year of antipsychotic treatment." (PMID 40896214, 2025). "High plasma prolactin levels are associated with poorer cognitive functioning in early psychosis; however, the effects of prolactin on cognitive function are still unclear." (PMID 38999843, 2024). "Duration of illness/psychosis in patients treated with anti-psychotic medication appeared to be associated with prolactin levels." (PMID 35223307, 2022). "Another study demonstrated that FEP patients have significantly higher levels of prolactin, fasting glucose, glycosylated hemoglobin and insulin resistance compared to individuals at clinical high risk of psychosis." (PMID 32547431, 2020). "An increase in prolactin levels was associated with female gender, while the use of prolactin sparing antipsychotics and a duration of psychosis over 10 years were associated with lower prolactin levels." (PMID 32017792, 2020). "Prolactin levels were negatively associated with cognitive performance in processing speed, in patients with a psychotic disorder and high-risk subjects." (PMID 24586772, 2014). "It was found that in patients with early psychosis, higher prolactin levels were associated with slower processing speed, and prolactin may be involved in the pathological process of cognitive impairment in patients with BD." (PMID 38773397, 2024). "Interestingly, altered release of hormones that are regulated by the pituitary gland, such as cortisol and prolactin has been implicated in psychotic disorders." (PMID 38357733, 2024). "It has been suggested that prolactin may underlie the excess of morbidity and early mortality in naïve patients with a first episode of psychosis through a specific pathway that intertwines inflammatory, immune and metabolic trajectories." (PMID 34945748, 2021). "The main aim of our study was to explore whether prolactin levels are associated with poorer cognitive functioning in subjects with early psychoses, including both first episode of psychosis and high-risk subjects." (PMID 24586772, 2014). "Thus, prolactin levels may reveal the pathogenic process (the psychosis related hyperdopaminergic state) and, in patients receiving treatment, the antipsychotic biological activity." (PMID 32017792, 2020). "This case emphasizes lurasidone’s potential utility in youth with psychosis who are sensitive to weight gain, sedation, and prolactin-related adverse effects." (PMID 40732269, 2025). "In conclusion, we report the protective role of increased PRL levels against oxidative stress in patients with psychosis treated with risperidone and paliperidone." (PMID 39061992, 2024). "In the present study, we analyzed PRL levels, reactive oxygen species, and enzymes of the antioxidant system in patients with psychosis treated with risperidone and paliperidone." (PMID 39061992, 2024). "Patients at first episode psychosis showed significantly higher levels of blood glucose and prolactin levels, while chronic patients showed significantly higher LDL levels." (PMID 38928058, 2024). "A recent systematic review and meta-analysis examined evidence from open-label studies and randomized clinical trials on four prolactin-lowering strategies in patients suffering from psychotic disorders." (PMID 37759839, 2023). "Due to it being the first episode of psychosis, an MRI was performed, which found a 1.6 cm macroadenoma and a prolactin level of 1,986.5 ng/mL." (PMID 38143631, 2023). "Nevertheless, there have been reports of high prolactin levels in drug-naive patients with SZ or other psychotic disorders, as well as in BD." (PMID 35546954, 2022). "It is reported women with psychotic disorders taking antipsychotic medications have some risk factors for low BMD including low BMI, prolactin level, low vitamin D, and serotonergic antidepressant use." (PMID 36684026, 2022).
psychosis (continued). "The aim of the study was to investigate the level of prolactin response to antipsychotic treatment in acute patients, taking into account the total duration of psychosis." (PMID 32017792, 2020). "Antipsychotic medication, stress, gender, and age are factors that influence prolactin levels in patients with psychosis." (PMID 32017792, 2020). "At this purpose an important concern involves the relationship between stress, psychosis onset and increased release of PRL." (PMID 30068291, 2018). "The two most recent studies to be published both found elevated plasma prolactin in drug-naïve patients with first-episode psychosis, while older studies found lower or equivalent levels." (PMID 24800074, 2014). "The case highlights the importance of the role of prolactin in psychosis and of an interdisciplinary team approach when patients present with complex symptoms." (PMID 22937400, 2011). "Although the biological pathways linking stress and psychosis are complex and multifactorial, alterations in prolactin regulation may represent one of the mechanisms contributing to this association." (PMID 40896214, 2025). "The aim was to determine whether CT influence metabolic profiles and prolactin levels in patients with first-episode psychosis treated with antipsychotics for up to one year." (PMID 40896214, 2025). "However, animal studies suggest that prolactin has a direct effect on the mesolimbic dopamine system, which is involved in the pathophysiology of psychosis." (PMID 40896214, 2025). "Therefore, our study aimed to examine if there is any connection between risperidone/paliperidone, increased PRL levels, and ROS parameters in patients diagnosed with psychotic disorders." (PMID 39061992, 2024). "This study aims to investigate the intensity of prolactin response to antipsychotic treatment in inpatients with psychosis, considering the total duration of the illness and other factors that might have an impact on prolactin serum levels in these patients." (PMID 32017792, 2020). "In patients with a DP between 5 and 10 years, the sex ratio was 2:1 in favor of women, and the level of psychosis induced stress was similar to the other two groups, so again, an important prolactin rise should be expected, but these subjects received mainly prolactin sparing antipsychotics." (PMID 32017792, 2020). "The aim of this study was to compare prolactin levels, glycometabolism parameters and lipid profile between a sample of 31 drug-naive adolescents in the acute phase of FEP and a control group of 23 subjects at clinical high risk (CHR) of developing psychosis." (PMID 30068291, 2018). "Additionally, further studies are needed to confirm or refute prolactin's role in the development of psychosis." (PMID 30627169, 2018). "Prolactin elevations with antipsychotic treatments were well studied; however, the lion's share of the research has been conducted on adult patients with first episodes of psychosis." (PMID 29805808, 2018). "It is hypothesized that the increase in dopamine in psychosis may be, in part, a regulatory response to down regulate the stress-induced rise in prolactin." (PMID 30627169, 2018). "In summary, our study suggests that increased prolactin levels are associated with impaired processing speed in early psychosis and that also mediate the negative effects of prolactin elevating antipsychotics on processing speed." (PMID 24586772, 2014). "They suggest that stress leads to an increased level of prolactin, which triggers dopamine release by a feedback mechanism; this increase in dopamine transmission may mediate the link between stress and psychosis." (PMID 24800074, 2014). "Our study suggests that increased prolactin levels are associated with impaired processing speed independent of antipsychotic drugs in subjects with early psychosis." (PMID 24586772, 2014).